DISP2 (dispatched RND transporter family member 2)
Synonyms: C15orf36; DISPB; KIAA1742; LINC00594; HsT16908
Tractability: Antibody: its Gene Ontology location is reachable by antibodies, with high confidence; UniProt predicts a signal peptide or a membrane-spanning region. PROTAC: ubiquitination databases record sites on it; its protein half-life has been measured.
Gene: Protein-coding gene on chromosome 15 (40,358,219 to 40,378,621, forward strand). Ensembl gene ENSG00000140323.
Subcellular location: Membrane
Subcellular location (Human Protein Atlas): Nucleoplasm; Vesicles
Pathways (Reactome):
Signal Transduction: Release of Hh-Np from the secreting cell
Gene Ontology:
Biological process: smoothened signaling pathway
Cellular component: membrane; plasma membrane
Genetic constraint (gnomAD): Loss-of-function variants: 58 observed, 88.8 expected, observed/expected ratio (o/e) 0.65, 90% interval 0.53 to 0.81. The upper end of that interval is the gene's LOEUF score, 0.81, which puts it in group 3 of 6, group 1 being the genes least tolerant of losing a copy. Missense variants: 1,747 observed, 1,779.9 expected, observed/expected ratio (o/e) 0.98, 90% interval 0.94 to 1.02. Synonymous variants: 823 observed, 777.12 expected, observed/expected ratio (o/e) 1.06, 90% interval 1 to 1.12.
Homologues: Orthologues: chimpanzee DISP2 (99% identical), macaque DISP2 (98% identical), dog DISP2 (89% identical), pig DISP2 (89% identical), rabbit DISP2 (82% identical), guinea pig DISP2 (80% identical), rat Disp2 (74% identical), mouse Disp2 (73% identical), tropical clawed frog disp2 (51% identical), zebrafish disp2 (44% identical), Drosophila melanogaster disp (23% identical), Caenorhabditis elegans ptd-2 (13% identical), and 4 more. Paralogues in human: DISP1 (35% identical), NPC1L1 (13% identical), SCAP (13% identical), PTCH1 (12% identical), NPC1 (11% identical), PTCH2 (11% identical), PTCHD3 (9% identical), DISP3 (9% identical), PTCHD1 (8% identical), PTCHD4 (7% identical).
Diseases named in the same sentence as DISP2 in open-access papers:
DISP2 is named in the same sentence as 9 diseases in open-access papers, as found by Europe PMC text mining. Sharing a sentence is not in itself a finding about the gene and the disease. The quoted sentences say what the papers report.
lung carcinoma (2 papers, 2020 to 2023). "GWAS have identified DISP2-related risk loci for lung cancer, as well as for diverticular disease." (PMID 37369878, 2023). "Predicted expression of seven genes was significantly (p < 5.0 × 10−4) associated with lung cancer risk: SECISBP2L, HLA-L, DISP2, MAPT, KANSL1-AS1, LRRC37A4P, and PLEKHM1." (PMID 31911640, 2020).
esophageal cancer (1 paper, 2023). A primary or metastatic malignant neoplasm involving the esophagus. "Recently, DISP2 was found downregulated in low grade glioma, as well as in an esophageal cancer cell line, suggesting a putative role as a tumor-suppressor protein." (PMID 37369878, 2023).
squamous carcinoma (1 paper, 2020). "Effects observed for DISP2 (OR = 1.21, p = 0.021) and HLA-L (OR = 0.90, p = 0.034) were attenuated for adenocarcinoma, but not for squamous carcinoma (DISP2: OR = 1.30, p = 6.2 × 10−3; HLA-L: OR = 0.75, p = 1.6 × 10−6)." (PMID 31911640, 2020).
cancer (2 papers, 2020 to 2025). A tumor composed of atypical neoplastic, often pleomorphic cells that invade other tissues. "DISP2 encodes a protein related to proteasome-mediated degradation and signalling by Hedgehog leads to pathological consequences in cancers, and PWP2 has been found to promote in-vitro invasion and migration of cancer cell lines." (PMID 40622919, 2025).
infection (2 papers, 2017 to 2021). The state of being infected such as from the introduction of a foreign agent such as serum, vaccine, antigenic substance or organism. "The response proteins DISP2 and NAA15 were among the most upregulated molecules, finding higher levels of expression at later stages of the infection." (PMID 28491823, 2017).
DISP2 also shares sentences with these, for which no sentence is quoted: adenocarcinoma (1 paper); diverticular disease (1); glioma (1); tumor (1).